PRPF39 (pre-mRNA processing factor 39)
Description:
Involved in pre-mRNA splicing.
Synonyms: FLJ20666; FLJ11128
Tractability: PROTAC: ubiquitination databases record sites on it; its protein half-life has been measured.
Gene: Protein-coding gene on chromosome 14 (45,084,107 to 45,116,282, forward strand). Ensembl gene ENSG00000185246.
Subcellular location: Nucleus
Subcellular location (Human Protein Atlas): Nucleoplasm
Gene Ontology:
Molecular function: protein binding; pre-mRNA 5'-splice site binding
Biological process: mRNA 5'-splice site recognition; RNA processing
Cellular component: commitment complex; U1 snRNP; U2-type prespliceosome; nucleus
Genetic constraint (gnomAD): Loss-of-function variants: 21 observed, 62.84 expected, observed/expected ratio (o/e) 0.33, 90% interval 0.24 to 0.48. The upper end of that interval is the gene's LOEUF score, 0.48, which puts it in group 2 of 6, group 1 being the genes least tolerant of losing a copy. Missense variants: 550 observed, 714.8 expected, observed/expected ratio (o/e) 0.77, 90% interval 0.72 to 0.83. Synonymous variants: 247 observed, 227.76 expected, observed/expected ratio (o/e) 1.08, 90% interval 0.98 to 1.21.
Homologues: Orthologues: chimpanzee PRPF39 (99% identical), macaque PRPF39 (99% identical), dog PRPF39 (97% identical), rabbit PRPF39 (97% identical), pig PRPF39 (96% identical), guinea pig PRPF39 (95% identical), rat Prpf39 (94% identical), mouse Prpf39 (94% identical), tropical clawed frog prpf39 (65% identical), zebrafish prpf39 (63% identical), Drosophila melanogaster CG42272 (14% identical).
Diseases named in the same sentence as PRPF39 in open-access papers:
PRPF39 is named in the same sentence as 6 diseases in open-access papers, as found by Europe PMC text mining. Sharing a sentence is not in itself a finding about the gene and the disease. The quoted sentences say what the papers report.
liver cancer (3 papers, 2021). An epithelial or non-epithelial malignant neoplasm that arises from the liver. "PRPF39 is a regulator of cisplatin sensitivity in liver cancer." (PMID 34738869, 2021).
Myotonia (1 paper, 2025). An involuntary and painless delay in the relaxation of skeletal muscle following contraction or electrical stimulation. "Interestingly, several splicing factors including Srsf6, Prpf39, Rbm7, Tra2b, Rbfox2, and Hnrnpu, exhibited alternative splicing in Mbnl1−/− mice with myotonia, but not in those without." (PMID 41000779, 2025).
Schindler disease (1 paper, 2013). "Mutations in NAGA have been associated with Schindler disease, whereas mutations in PRPF39 have not been correlated with any specific disease." (PMID 23890092, 2013).
cancer (2 papers, 2021 to 2023). A tumor composed of atypical neoplastic, often pleomorphic cells that invade other tissues. "In addition, some reported factors, including E2F5, PTEN/AKT/mTOR signaling, DUSP11, PRPF39, and LARP4, are involved in miR-513b-5p regulated cancer progression." (PMID 34120890, 2021).
PRPF39 also shares sentences with these, for which no sentence is quoted: tumor (2 papers); bladder cancer (1).